ISX (intestine specific homeobox)
Description:
Transcription factor that regulates gene expression in intestine. May participate in vitamin A metabolism most likely by regulating BCO1 expression in the intestine (By similarity).
Synonyms: RAXLX; Pix-1
Tractability: No criterion of Open Targets' tractability assessment is met for any kind of drug.
Gene: Protein-coding gene on chromosome 22 (35,066,136 to 35,087,392, forward strand). Ensembl gene ENSG00000175329.
Subcellular location: Nucleus
Subcellular location (Human Protein Atlas): Nucleoplasm; Nuclear bodies
Gene Ontology:
Molecular function: protein binding; sequence-specific double-stranded DNA binding; DNA-binding transcription factor activity, RNA polymerase II-specific; RNA polymerase II transcription regulatory region sequence-specific DNA binding; DNA binding; DNA-binding transcription repressor activity, RNA polymerase II-specific; sequence-specific DNA binding
Biological process: neuron development; regulation of transcription by RNA polymerase II; negative regulation of transcription by RNA polymerase II; regulation of DNA-templated transcription
Cellular component: nuclear body; nucleoplasm; chromatin; nucleus
Genetic constraint (gnomAD): Loss-of-function variants: 11 observed, 12.65 expected, observed/expected ratio (o/e) 0.87, 90% interval 0.55 to 1.44. The upper end of that interval is the gene's LOEUF score, 1.44, which puts it in group 5 of 6, group 1 being the genes least tolerant of losing a copy. Missense variants: 287 observed, 287.53 expected, observed/expected ratio (o/e) 1, 90% interval 0.91 to 1.1. Synonymous variants: 116 observed, 112.14 expected, observed/expected ratio (o/e) 1.03, 90% interval 0.89 to 1.21.
Homologues: Orthologues: chimpanzee ISX (99% identical), macaque ISX (93% identical), dog ISX (69% identical), rabbit ISX (68% identical), rat Isx (64% identical), pig ISX (63% identical), mouse Isx (50% identical), tropical clawed frog isx (34% identical). Paralogues in human: ARX (32% identical), RAX (29% identical), VSX2 (29% identical), ALX4 (25% identical), DMBX1 (25% identical), ALX1 (24% identical), ALX3 (24% identical), PAX7 (24% identical), SHOX (24% identical), SHOX2 (24% identical), UNCX (24% identical), OTP (24% identical), and 38 more.
Diseases named in the same sentence as ISX in open-access papers:
ISX is named in the same sentence as 13 diseases in open-access papers, as found by Europe PMC text mining. Sharing a sentence is not in itself a finding about the gene and the disease. The quoted sentences say what the papers report.
hepatoma (9 papers, 2016 to 2023). "ISX, a pair‐family homeobox TF, is a pro‐inflammatory cytokine (IL‐6)‐induced homeobox gene that is highly expressed in hepatoma cells from patients with hepatocellular carcinoma (HCC)." (PMID 31908141, 2020). "Ablation of AHR or ISX in hepatoma cells suppresses cell growth, whereas its overexpression promotes cell proliferation and leads to enhanced in vitro and in vivo tumorigenic activity." (PMID 29301348, 2018). "Intestine-specific homeobox (ISX), a newly identified proto-oncogene, is involved in cell proliferation and progression of hepatocellular carcinoma (HCC)." (PMID 27175585, 2016). "Intestine-specific homeobox (ISX), a newly identified proto-oncogene, regulates cell proliferation and drives hepatocellular carcinoma (HCC) formation via cyclin D1 upregulation under stimulation by proinflammatory cytokines such as IL-6." (PMID 27175585, 2016). "The E2F1 promoter region between −168 and +31 was pulled down by an anti-ISX antibody and was shown to correlate with the expression level of E2F1 in hepatoma cells, particularly in Hep3B and SK-Hep1 cells." (PMID 27175585, 2016). "The hepatoma cells (Huh 7 and SNU‐423) treated with NF‐κB inhibitor inhibited the enhancements of TG, glucose, kynurenine, and PD‐L1 induced by the GFP‐core protein as well as MAPK inhibitor (U0126) treatment, an inhibitor of ISX phosphorylation." (PMID 37316966, 2023). "IL-6 could upregulate the intestine-specific homeobox (ISX) gene to induce the expression of IDO1 and TDO, and promote the malignant potential of hepatocellular carcinoma cells." (PMID 33883013, 2021). "Upregulated and nuclear-localized E2F1 (red), as the overexpressed ISX protein (green), was detected mainly in the nucleus (blue) of Hep 3B cells with forced ISX expression (yellow arrow) rather than in neighbor hepatoma cells without overexpressed ISX." (PMID 27175585, 2016).
lung carcinoma (3 papers, 2020 to 2023). "Apart from HCC development, ISX expression was associated with the risk of gastric cancer, lung cancer, and the survival of pancreatic cancer patients." (PMID 37349365, 2023). "In lung cancer, ISX is acetylated by the presence of p300/CBP-associated factor and then interacts with acetylated bromodomain‐containing protein 4 to regulate tumour initiation and metastasis." (PMID 37349365, 2023). "The expression of both BRD4 (red) and PCAF (red) was co‐localized with ISX expression (green) in lung cancer cells (yellow arrow)." (PMID 31908141, 2020). "Moreover, analysis of six lung cancer cell lines (A549, H358, H441, H1299, H1435, and H1437) revealed that the mRNA and protein expression patterns of ISX, PCAF, and BRD4 were co‐expressed in lung cancer cells relative to those in human diploid lung fibroblasts (WI38; Fig EV1D and E)." (PMID 31908141, 2020). "According to a previous study, p300/CBP‐associated factor (PCAF) mediated epithelial–mesenchymal transition (EMT) and promotes cancer metastasis by recruiting intestine‐specific homeobox (ISX) and bromodomain‐containing protein 4 (BRD4) in lung cancer." (PMID 34173348, 2021). "The interaction between ISX, PCAF, and BRD4 was further evaluated in tumors and adjacent healthy lung tissues from patients with lung cancer." (PMID 31908141, 2020).
colon cancers (1 paper, 2020). "TF factors including ISX (suppressed ~ 2.3 fc in both), contain these binding motifs, suggesting an observed loss of these site-specific TFs might dictate de-novo hypermethylation and suppression of its downstream targets, in a side independent manner within colon cancers." (PMID 32293332, 2020).
liver cancer (1 paper, 2021). An epithelial or non-epithelial malignant neoplasm that arises from the liver. "The correlation of the gene expression (PCAF, ISX, and BRD4) in liver cancer is also being investigated." (PMID 34173348, 2021). "Although the mRNA expression of ISX strongly correlates with those of BRD4 and PCAF in patients with HCC, denoting that they were co‐expressed in liver cancer cells, the interaction between ISX, BRD4, and PCAF remains to be at issue." (PMID 34173348, 2021).
tumor (5 papers, 2016 to 2023). "Though several papers have reported that ISX is important in tumor progression HCC, the specific mechanism by which ISX is involved in carcinogenesis has yet to be fully clarified." (PMID 37444447, 2023). "Through direct regulation of cyclin D1 and E2F1 expression, ISX regulated the proliferation of tumour cells and their transforming activity." (PMID 37349365, 2023). "Mechanistically, PCAF acetylation of ISX at lysine 69 promotes the interaction with acetylated bromodomain‐containing protein 4 (BRD4) at lysine 332 in tumor cells, and the translocation of the resulting complex into the nucleus." (PMID 31908141, 2020). "Significant differences in tumor sizes, metastases, and cancer stages were observed between patients with high and low levels of ISX or BRD4 expression." (PMID 31908141, 2020). "E2F1 (red) and ISX (green) were more strongly expressed and colocalized in tumor masses than those in adjacent healthy liver tissues in samples obtained from HCC patients." (PMID 27175585, 2016). "The present study shows that the oncogenic transcription factor ISX is a key regulator of EMT and tumor metastasis by modulating the expression of EMT regulators, such as TWIST1 and Snail1." (PMID 31908141, 2020). "Confocal fluorescence imaging was then used to examine the interaction between ISX, BRD4, and PCAF in immunostained samples of tumor masses and adjacent healthy lung tissues from patients with NSCLC." (PMID 31908141, 2020). "Here, we show that the mRNA expression of PCAF, BRD4, and ISX in 377 paired specimens from patients with HCC, and the adjacent normal tissues exhibited a tumor‐specific expression pattern, highly correlated with disease pathogenesis, patient survival time, progression stage, and poor prognosis." (PMID 34173348, 2021). "The mRNA expression of E2F1 and ISX in 238 paired specimens from human HCC patients, and the adjacent, normal tissues exhibited a tumor-specific expression pattern which was highly correlated with disease pathogenesis, patient survival time, progression stage, and poor prognosis." (PMID 27175585, 2016).
cancer (4 papers, 2020 to 2023). A tumor composed of atypical neoplastic, often pleomorphic cells that invade other tissues. "The ISX gene is a new member of the homeobox superfamily, and the evidence of its effect on cancer aetiology has been carefully evaluated." (PMID 37349365, 2023). "Modulating the target gene expression of EMT regulators driven by PCAF–TF (ISX)–BRD4 clearly demonstrates a mechanistically synergistic regulatory effect on cancer metastasis." (PMID 31908141, 2020). "The expression of ISX, BRD4, and PCAF mRNA in HCC cells and cells from cancer patients was quantified using an SYBR Green Quantitative RT–PCR kit (Invitrogen)." (PMID 34173348, 2021). "Ectopic ISX expression enhances EMT marker expression, including TWIST1, Snail1, and VEGF, induces cancer metastasis, but suppresses E‐cadherin expression." (PMID 31908141, 2020). "Here, we show that p300/CBP‐associated factor (PCAF)‐dependent acetylation of the transcription factor intestine‐specific homeobox (ISX) regulates epithelial–mesenchymal transition (EMT) and promotes cancer metastasis." (PMID 31908141, 2020). "However, cancer cells with ISX knockdown did not exhibit enhanced cell migration and invasion induced by ISX." (PMID 31908141, 2020).
infection (2 papers, 2023 to 2025). The state of being infected such as from the introduction of a foreign agent such as serum, vaccine, antigenic substance or organism. "Blocking VSIR or ISX with specific RNAi abolished SARS-2-S–induced inflammation and metabolic disturbances, underscoring the critical role of the VSIR–ISX axis in maintaining immune–metabolic balance during infection." (PMID 41417109, 2025). "The transcriptomic and multiple evidences reveal that the HCV core protein–intestine‐specific homeobox (ISX) axis promotes a spectrum of metabolic, fibrogenic, and immune modulators (e.g., kynurenine, PD‐L1, and B7‐2), regulating HCV‐infection relevant pathogenic phenotype in vitro and in vivo." (PMID 37316966, 2023).
hematological cancer (1 paper, 2021). "We identified recurrent highly pathogenic variants affecting important drivers of hematological cancer (ATM), epigenetic regulators (ISX and SETDB1), and mediators of DNA replication (POLQ)." (PMID 33809641, 2021).
ISX also shares sentences with these, for which no sentence is quoted: COVID-19 (1 paper); gastric cancer (1); Hepatitis (1); immune dysfunction (1); pancreatic cancer (1).